CXCL9 (C-X-C motif chemokine ligand 9)
Diseases named in the same sentence as CXCL9 in open-access papers (continued):
Sharing a sentence is not in itself a finding about the gene and the disease.
dilated cardiomyopathy (2 papers, 2019 to 2022). Cardiomyopathy which is characterized by dilation and contractile dysfunction of the left and right ventricles. "While CXCL9, CXCL10, and CXCL11 belong to the chemokine family, CX3CR1, ADORA3 and SAA1 have not been reported in dilated cardiomyopathy, and further research is needed." (PMID 35618744, 2022).
eczema (2 papers, 2017 to 2019). "Eczema was associated with decreased concentrations of IFNα, IFNγ, TSLP, CXCL9, and CXCL13, but increased concentrations of CCL18 and Galectin-3." (PMID 31998285, 2019). "In skin lesions from eczema, the mean percentages of inflammatory cells expressing CXCL9, CXCL10, CXCL11 and CXCR3 were 4.8% ± 5.8%, 5.2% ± 6.3%, 63.2% ± 15.7% and 25.2% ± 13.0%, respectively." (PMID 28436448, 2017). "In addition, eczema was associated with decreased concentrations of IFNα, IFNγ, TSLP, CXCL9, and CXCL13, but with increased concentrations of CCL18 and Galectin-3." (PMID 31998285, 2019). "Moreover, we found that children with doctor's diagnosed eczema had limited capacity to induce Th1 cytokines (like IFN-gamma and CXCL9) and more eczema/skin related marker CCL18 (PARC)." (PMID 31998285, 2019).
endotoxemia (2 papers, 2020 to 2023). "Finally, we identified and verified 9 key genes (Cd274, Cxcl1, Cxcl9, Icam1, Ifit2, Isg15, Stat1, Tlr2, and Usp18), and we predicted seven potential drugs for multi-organ damage in LPS-induced endotoxemia." (PMID 33330617, 2020). "Cytokine storm and endotoxemia may cause a decrease in LV EF, but some chemokines (CXCL9 and CXCL10) suggest a direct negative inotropic effect." (PMID 36124439, 2023).
esophageal adenocarcinoma (2 papers, 2020). A malignant tumor with glandular differentiation arising predominantly from Barrett mucosa in the lower third of the esophagus. "Chemokine-receptor axes like the CXCL9, -10,-11/CXCR3- are prominent in esophageal adenocarcinoma with a fold change of up to 9.5 promoting cancer cell proliferation and metastasis." (PMID 31960110, 2020).
Ewing sarcoma (2 papers, 2021 to 2023). A small round cell tumor that lacks morphologic, immunohistochemical, and electron microscopic evidence of neuroectodermal differentiation. "Upon activation, NK cells secrete IFNγ, which feeds back on USP6-expressing Ewing sarcoma cells to synergistically induce CXCL9/CXCL10." (PMID 37615015, 2023). "Synergistic induction of CXCL9/CXCL10 was completely ablated by IFNGR1 depletion, and partly inhibited by IFNAR1 depletion, indicating that Ewing sarcoma–intrinsic signaling through both pathways contributes to this feedforward loop." (PMID 37615015, 2023). "Furthermore, USP6-expressing Ewing sarcoma and NK cells participate in a paracrine immunostimulatory feedforward loop, wherein IFNγ secreted by activated NK cells feeds back on USP6/Ewing sarcoma cells to induce synergistic expression of chemokines CXCL9 and CXCL10." (PMID 37615015, 2023).
graft versus host disease (2 papers, 2020 to 2024). An immune system disorder that occurs after allogeneic hematopoietic stem cell transplant and is a reaction of donor immune cells against host tissues. "CXCL9 can be also positive in patients with graft-versus-host disease." (PMID 38910713, 2024). "The presence of these factors is in agreement with higher capacity of IFNγ-inflamed MSCs to recruit T cells at their proximity and ability to reduce the symptoms of graft-versus-host disease (GVHD) in a mouse model, being CCL8 and CXCL9/10 upregulated in the mouse system after inflammation." (PMID 32345351, 2020).
hemophagocytic lymphohistiocytosis (2 papers, 2023). "Genetic tests for familial hemophagocytic lymphohistiocytosis and autoinflammatory disease showed no significant mutations, while the levels of CXCL-9, CXCL-10 and IL-18 resulted elevated." (PMID 37848930, 2023).
hepatitis B (2 papers, 2019 to 2022). "In addition, inflammatory neutrophils may directly express CXCL9 and CXCL10, which has been previously shown to impact recruitment of inflammatory T cells in transgenic mice that replicate hepatitis B." (PMID 36248905, 2022).
idiopathic dilated cardiomyopathy (2 papers, 2019 to 2021). Decreased function of the heart associated with cardiac enlargement and congestive heart failure, of unknown cause. "A recent study of patients with idiopathic dilated cardiomyopathy showed that an increased serum CXCL9 was associated with worsening ventricular dysfunction." (PMID 31083544, 2019).
idiopathic pulmonary arterial hypertension (2 papers, 2022 to 2024). A sporadic form of pulmonary arterial hypertension (PAH) characterized by elevated pulmonary arterial resistance leading to right heart failure. "CXCL9 has been reported to be upregulated in inflammatory colitis, and the increased CXCL9 expression was obviously associated with the survival and prognosis of patients with idiopathic pulmonary arterial hypertension (PAH) and chronic thromboembolic pulmonary arterial hypertension (CTEPAH)." (PMID 36309899, 2022).
infectious keratitis (2 papers, 2022 to 2023). "Along these lines, mice that are deficient in CXCR3, the receptor for CXCL9, have less severe keratitis, indicating that the CXCL9 receptor is also a critical mediator of the pathological immune response in viral keratitis." (PMID 38274739, 2023). "We identified several specific genes and pathways involved in the host response to infectious keratitis, including CXCL9, CXCR3, and MMP9 for viral, and S100A8/A9, MMP9, and the IL17 pathway for bacterial/fungal keratitis." (PMID 38274739, 2023). "We identified several genes and pathways involved in the host response to infectious keratitis, including CXCL9, CXCR3, and MMP9 for viral, and S100A8/A9, MMP9, and the IL17 pathway for bacterial/fungal keratitis." (PMID 38274739, 2023).
interstitial nephritis (2 papers, 2017 to 2025). Inflammation of the renal tubules and supporting tissues of the kidney. "We have previously shown that urinary presepsin increases in interstitial nephritis; however, whether it is elevated in the conditions mentioned as confounding factors for CXCL9 and CXCL10 remains unclear and warrants further investigation." (PMID 41306150, 2025).
intestinal tumors (2 papers, 2018 to 2020). "Our previous study indicated that CXCR3-mediated chemotaxis may be an important means of T-cell recruitment into intestinal tumors as Treg depletion increased the production of CXCL9 and CXCL10 selectively in the tumors." (PMID 29671006, 2018). "This is the first time CXCR3 has been shown to be non-redundant for CD4+ T-cell migration into intestinal tumors, even though earlier results have indicated that CXCL9 and CXCL10 significantly correlate to disease free survival of CRC patients, and also to the recruitment of memory T cells." (PMID 29671006, 2018).
ischemic stroke (2 papers, 2025 to 2026). A stroke disorder caused by obstruction of blood flow to the brain, due to thrombotic (local blood clot formation) or embolic (due to a blood clot or other material traveling from another site) event. "In ischemic stroke, CXCL9 works to break down the blood-brain barrier, which leads to edema." (PMID 41497421, 2026).
kidney cancer (2 papers, 2007 to 2022). Primary or metastatic malignant neoplasm involving the kidney. "Thus, high CXCL9 expression is associated with prolonged overall survival in various malignancies, such as kidney cancer and pancreatic ductal adenocarcinoma." (PMID 36479091, 2022). "Some experts used immunohistochemical techniques to detect CXCL9 expression in kidney cancer tissues and found that CXCL9 expression was negatively correlated with tumor size and microvessel density, and positively correlated with the number of CD8+ T cells infiltrating the tumor." (PMID 36479091, 2022).
leprosy (2 papers, 2019 to 2025). Leprosy is a chronic infectious disease affecting primarily the skin and peripheral nervous system. "Among patients with leprosy, higher CXCL9 levels were observed in patients with high bacillary loads." (PMID 40683203, 2025).
leukemia (2 papers, 2014 to 2019). A malignant (clonal) hematologic disorder, involving hematopoietic stem cells and characterized by the presence of primitive or atypical myeloid or lymphoid cells in the bone marrow and the blood. "As we know, CXCR3’s ligands included CXCL10 (IP-10) and CXCL11 (I-TAC), and few researches about CXCL9.CXCL10 was selected through stimulating leukemia U937cell lines from the DNA pool by Luster who comes from American." (PMID 30973890, 2019).
leukoplakia (2 papers, 2015 to 2021). A white patch or plaque on a mucous membrane that cannot be characterized clinically or pathologically as any other disease. "We previously showed that human oral leukoplakia, a premalignant oral lesion, is a Th1-dominated tumor microenvironment that shows increased CXCL9 expression and infiltration of CXCR3+ and CCR5+ cells." (PMID 33921389, 2021). "In fact, our immunohistochemical analysis demonstrated that CXCL9 was present in the subepithelial lesion of leukoplakia." (PMID 26242181, 2015). "Cells positive for the IFN-inducible chemokine CXCL9 were also observed in the subepithelial lesion of leukoplakia." (PMID 26242181, 2015).
liver failure (2 papers, 2015 to 2021). A liver disease characterized by the liver losing or has lost all of its function. "It is also interesting to note that ADIPOQ, β-NGF, CXCL1, CXCL9, CXCL12, IL-16, and PECAM-1 are up-expressed only in those CHC and HCC patients who present a liver failure, and, hence, linkable to the necro-inflammatory activity of the liver." (PMID 26226632, 2015).
mastitis (2 papers, 2020 to 2025). Inflammation of breast tissue during lactation or postpartum due to an obstructed duct or infection. "It has been reported that breast milk from women with subclinical mastitis exhibits a predominant Th1/proinflammatory cytokine profile, including TNF-α, IL-6, IL-8, IL-17, RANTES, IL-12p40/70, IFN-α, IFN-γ, CXCL-9, IP-10, MIP-1α, and MIP-1β." (PMID 40564173, 2025).
meningeal TB (2 papers, 2009 to 2012). "The increase in CXCL9 observed in severe extrapulmonary disease corresponds with literature which have shown chemokines responses to be increased in severe TB such as in tuberculous meningitis." (PMID 19340290, 2009). "Among potential clinical signatures reported are CXCL9, CXCL10, CCL1, and IL11, as their expression levels could differentiate some kinds of clinical manifestations such as latent TB, pulmonary, and meningeal TB." (PMID 22675550, 2012).
metastatic cancer (2 papers, 2020 to 2023). A carcinoma which has spread from the original site of growth to another anatomic site. "Together, these results indicate that JNK-driven production of IL-1α/β by metastatic cancer cells induces CXCL9/10 in pulmonary MAFs to form a supportive metastatic niche." (PMID 32198421, 2020).
morphea (2 papers, 2019 to 2024). "Moreover, elevated levels of CXCL9 and CXCL10 were detected in the serum of patients with morphea, consistent with increased transcription and expression of CXCL9 in skin lesions, and this increase has been linked to inflammation and disease activity." (PMID 39685593, 2024).
mucositis (2 papers, 2017 to 2019). Mucositis is inflammation and damage of the mucous membranes lining the mouth and other parts of the gastrointestinal (GI) tract. "CXCL9 treatment has been disclosed to attenuate 5-Fu induced mucositis, however, it exacerbates 5-Fu induced acute intestinal damage." (PMID 29124041, 2017). "Therefore, further investigation is needed to clarify the effect of CXCL9 on 5-Fu induced mucositis." (PMID 29124041, 2017). "In 5-Fu-induced mucositis rodents, chemokines/cytokines such as chemokine-1, 2, 9 (CXCL1, CXCL2, CXCL9), and interleukine-4 (IL-4) are elevated, which is accompanied with intestinal epithelium damage." (PMID 29124041, 2017).
mycobacterial pulmonary infections (2 papers, 2012 to 2017). "Importantly, despite a common role for Lcn2 in regulating CXCL9 expression during mycobacterial pulmonary infections, Lcn2KO mice are more susceptible to acute M.bovis BCG pulmonary infection, but not low dose M.tuberculosis pulmonary infection." (PMID 23185529, 2012). "As was reported, pathogen specific Th17 cells generated during mycobacterium infection induce the expression of CXCL9, CXCL10 and CXCL11, as well as IL-17 produced dictate the migration of other important effectors cell types to control the infection." (PMID 29259310, 2017). "The new role for Lcn2 presented in this paper is to constrain CXCL9 induction and lymphocytic accumulation during mycobacterial pulmonary infections." (PMID 23185529, 2012). "In this study, we reveal a new role for Lcn2 in regulating lung inflammation and T cell accumulation during mycobacterial pulmonary infections, by restraining CXCL9 induction." (PMID 23185529, 2012). "In the present study, using models of acute and chronic mycobacterial pulmonary infections, we reveal a novel role for Lcn2 in constraining T cell lymphocytic accumulation and inflammation by inhibiting inflammatory chemokines, such as CXCL9." (PMID 23185529, 2012).
neuroblastoma (2 papers, 2020 to 2024). Neuroblastoma (NB) is the most common solid, extracranial childhood tumor. "In neuroblastoma (NB), MYCN-induced upregulation of the H3K9 methyltransferases G9a and GLP as well as EZH2 can also inhibit IFN-γ-induced expression of CXCL9 and CXCL10." (PMID 39080807, 2024).
pancreatic ductal adenocarcinoma (2 papers, 2021). An infiltrating adenocarcinoma that arises from the epithelial cells of the pancreas. "In addition, plasma CXCL9 has been found to predict the survival of patients with advanced pancreatic ductal adenocarcinoma receiving chemotherapy, potentially improving treatment outcomes." (PMID 34054929, 2021).
papilloma (2 papers, 2020 to 2024). A benign epithelial neoplasm that projects above the surrounding epithelial surface and consists of villous or arborescent outgrowths of fibrovascular stroma. "Flow cytometry analysis from papillomas at 4 weeks post-infection showed that the main CXCL9-producing cells were CD11b+F4/80+ macrophages and K14+ keratinocytes in both K17KO and WT papillomas." (PMID 31968015, 2020). "We found a novel regulator, stress keratin 17 (K17), was induced in expression following MmuPV1 infection, and that K17 was critical for preventing T cell infiltration in MmuPV1-induced papillomas by inhibiting the CXCL9/CXCL10/CXCR3 axis." (PMID 31968015, 2020). "In the K17KO papillomas, while we found significant induction of CXCL9 and CXCL10, there was a significant reduction in CXCL11 RNA level compared to WT papillomas (p = 0.0002)." (PMID 31968015, 2020). "We also confirmed upregulated expression of IFNγ-related genes by RT-qPCR, including IFNγ, PD-L1, CXCL9 and CXCL10 in K17KO papillomas." (PMID 31968015, 2020). "There were decreases in both infiltrating CD4 and CD8 T cells in the papillomas arising in K17KO blocked with anti-CXCR3, suggesting the increased infiltration of CD8+ T cells in K17KO mouse papillomas was mediated by the CXCL9/CXCL10/CXCR3 signaling axis." (PMID 31968015, 2020). "Cellular genes involved in immune response were differentially expressed in the papillomas arising on the K17KO mice correlating with increased numbers of infiltrating CD8+ T cells and upregulation of IFNγ-related genes, including CXCL9 and CXCL10, prior to complete regression." (PMID 31968015, 2020).
Pleural effusion (2 papers, 2012 to 2022). The presence of an excessive amount of fluid in the pleural cavity. "Our data show that CCL1, CXCL9 and IP-10 were highly expressed in both the periphery and the pleural effusions from tuberculous pleurisy patients." (PMID 23028695, 2012). "The CXCL9 expression level was upregulated among patients with a higher fever peak, fever duration of greater than 7 days, an imaging manifestation of lobar or segmental, or combined pleural effusion (All P<0.05)." (PMID 36532054, 2022). "The CXCL9 expression level was upregulated among patients with a higher fever peak, fever duration of greater than 7 days, an imaging manifestation of lobar or segmental, or combined pleural effusion (P<0.05)." (PMID 36532054, 2022). "We found the CXCL9 expression level was upregulated among patients with a higher fever peak, fever duration of greater than 7 days, an imaging manifestation of lobar or segmental, or combined pleural effusion, suggesting that the CXCL9 might have correlation with the disease severity." (PMID 36532054, 2022).
pneumococcal pneumonia (2 papers, 2018 to 2022). A febrile disease caused by STREPTOCOCCUS PNEUMONIAE. "Consistent with prior studies of remodeling after pneumococcal pneumonia, the AM from experienced lungs had increased Cxcl9 induction during infection compared with AM from infected lungs of naive mice." (PMID 35133985, 2022). "These experimental data altogether identified serum levels of CXCL9 and CXCL10 as powerful diagnostic biomarkers for pneumococcal pneumonia that should advance toward clinical validation in patient cohorts." (PMID 29988532, 2018).
pneumonitis (2 papers, 2024 to 2025). An inflammatory process affecting the lung parenchyma. "This entails the development of predictive biomarkers, such as dynamic changes in circulating cytokines (e.g., T-cell recruiting CXCL9/10 versus pro-inflammatory IL-6/IL-8) and the peripheral T-cell repertoire diversity, to stratify patients for benefit and pneumonitis risk." (PMID 41438748, 2025).
renal carcinoma (2 papers, 2010 to 2023). A carcinoma arising from the epithelium of the renal parenchyma or the renal pelvis. "Similarly, high expression of CXCL9/10 was observed in macrophage cells in renal cancer datasets, with a strong correlation with M1 macrophages in the KIRC and CM datasets." (PMID 37540227, 2023).
renal fibrosis (2 papers, 2021 to 2025). A final common manifestation of a wide variety of chronic kidney diseases characterized by glomerulosclerosis and tubulointerstitial fibrosis. "Also, IFN-I recruits leukocytes into renal tissues through the CXCL9/10/11-CXCR3A-Gi-PI3K-MAPK signaling pathway, enhancing renal fibrosis response." (PMID 33959133, 2021).